FOXP3 (forkhead box P3)
Diseases named in the same sentence as FOXP3 in open-access papers (continued):
Sharing a sentence is not in itself a finding about the gene and the disease.
tumor (continued). "Salet and Elkordab have suggested that Treg (FOXP3+) should be performed in subgroups based on their location in the tumor tissue and the current prognostic influence of each subgroup should be evaluated individually." (PMID 34876047, 2021). "The aim of our study was to determine the association between the number of positive lymph nodes and infiltrates of tumor-associated cytotoxic CD8 + (CTLs), regulatory FOXP3 + T cells (Tregs), as well as other prognostic factors." (PMID 34117905, 2021). "Secondly, as a tumor suppressor, FOXP3 represses many key target genes in cancer development and progression, such as HER2/ERBB2, BRCA1, SKP2, and CD44, providing a strong link between FOXP3 and cell cycle regulation as well as FOXP3 and DNA repair system." (PMID 34768829, 2021). "VEGF recruits CD4+ Foxp3+ Tregs to the tumor microenvironment by interacting with neuropilin 1 on their cell surface." (PMID 33746989, 2021). "GzmB and perforin were also reported to be expressed in FOXP3+ Tregs in mice, in particular in tumor models, but circulating human FOXP3+ Tregs express only very low levels of GzmB." (PMID 34910301, 2021). "These immune cells include tumor-associated macrophages, cytotoxic T cells, natural killer cells, B cells, CD4+CD25+FOXP3+ regulatory T cells, dendritic cells, and myeloid-derived suppressor cells." (PMID 33802331, 2021). "In contrast, CD4+Foxp3+ T cells, known as regulatory T cells (Tregs), which can hamper effective antitumor immunity, were significantly decreased in the tumor tissue of the ES-DSM + MW treated group." (PMID 34362890, 2021). "While IL-21 was able to inhibit cancer cell-mediated FOXP3 induction in the context of tumor supernatants, which was contrary to our study." (PMID 34026621, 2021). "The C4 subset was annotated as Treg cells based on the high expression signature genes of tumor-infiltrating Tregs (FOXP3, IL2RA, IL2RB, IL2RG, IL10RA, MAGEH1, LAYN, and GATA3)." (PMID 34663810, 2021). "Reduced HLA-class I expression and CD8+/Granz B+ T cells homeostasis are observed in tumor regions where FOXP3+ Treg and mast cells co-localize, with such features associated with resistance to anti-PD-1 treatment." (PMID 33436641, 2021). "In many kinds of neoplasms, especially solid tumors, large numbers of FoxP3+ Tregs infiltrate into tumors." (PMID 32203145, 2021). "In a previous study by our group, therapeutic vaccination was combined with either Foxp3 or CTLA4 gene silencing to enhance the antitumor response following B16 tumor cell transplantation." (PMID 33801683, 2021). "The results showed that the high expression of FOXP3 was negatively correlated with tumor number (P = 0.015) and TNM stage (P = 0.040), suggesting the inhibitory role of FOXP3 in HCC." (PMID 33116119, 2020). "T-bet+Foxp3+CD4+ T cells mediated by the immunosuppressive cytokine TGF-β accumulate in the lungs of tumour-bearing mice and are characterized as Th1-like Tregs." (PMID 32680511, 2020). "By contrast, we demonstrate that tumour nest located lymphocytes that are positive for CD8 (cytotoxic T cells) or FoxP3 (regulatory T cells) have exactly the opposite correlation with outcome, and only within ER-positive cases." (PMID 32577938, 2020). "FOXP3-expressing Tregs are reported to be abundant in tumor infiltrates and are involved in the immune escape mechanisms promoted by cancer." (PMID 32222891, 2020). "COX-2 inhibitors attenuate Treg cell activity and Foxp3 expression in tumor-infiltrating lymphocytes, enhancing antitumor response that results in the delay of tumor growth." (PMID 33050416, 2020). "Other markers (CD8, FOXP3, PD‐1, and PD‐L1) displayed similar expression in the primary tumor and matched lymph nodes." (PMID 32383556, 2020). "Low numbersof tumor infiltrating FOXP3+ T cells and high numbersof infiltrating CD8+ lymphocytes have been suggestedas favorable prognostic markers for invasive ductalcarcinoma of the breast." (PMID 31721539, 2020).
tumor (continued). "Tumour-infiltrating FOXP3 + lymphocytes and CD68 + macrophages were both predominant in tumours with high SLCs and to a lesser extent in those tumours with high SLC1A5 expression (p < 0.0001)." (PMID 31819174, 2020). "We observed high levels of tumor‐infiltrating T‐cell subsets, including CD8+ T cells, CD4+ T cells, CD4+FOXP3+ T cells and DNT cells, were associated with prolonged OS and RFS." (PMID 32377339, 2020). "Forkhead Box P3 (FoxP3) is considered a key transcription factor in Tregs, and is also expressed in several tumor cells." (PMID 32206186, 2020). "Grade 3 tumours showed significantly greater infiltration of CD20+, CD8+ and FoxP3+ lymphocytes within the stromal compartment (all p < 0.05), while this was significant in the tumour nests only for FoxP3+ lymphocytes (p = 0.008)." (PMID 32577938, 2020). "CTLA4 mAbs have been shown to enhance the anti-tumor immunity in humans by blocking activation of FOXP3+CD4+ Tregs." (PMID 32733457, 2020). "The association between the presence of FOXP3+ T lymphocytes and survival of CRC patients was extracted from fourteen studies stratified by tumor location, with eleven evaluating the CC, four the TS, and three the IM." (PMID 32099066, 2020). "Second is the opposite type, namely FoxP3-dominate hotspot, where the anti-tumor immunity is possibly impaired by Tregs." (PMID 33192595, 2020). "A correlation between IDO1 expression and FoxP3+ Treg lymphocytes density in the tumor microenvironment of PTCs was observed." (PMID 33986723, 2020). "Accordingly, the expression of PD-1 on Tregs correlates with their immunosuppressive activity, and the accumulation of PD1+Foxp3+ Tregs within the tumor microenvironment of solid tumors strongly supports their immunosuppressive potential." (PMID 32948017, 2020). "CD8+TIL density and Foxp3+TIL density were significantly higher in the stroma area than in the tumor are (P < .0001)." (PMID 32400056, 2020). "It has also been suggested that Tim3+Foxp3+ Treg cells represent specialized tumor resident Foxp3+ cells that probably have a role in T cell dysfunction." (PMID 32674255, 2020). "Among the most scrutinized immune cells, Forkhead Box Protein P3 (Foxp3)+ Regulatory T cells (Treg cells) are central inhibitors of protective anti-tumor immunity." (PMID 33143070, 2020). "Immunohistochemical staining of skin and tumor samples was performed to evaluate the presence of FoxP3+ and GrB+ cells." (PMID 32121641, 2020). "Bcl6 deletion significantly down regulates the expression of Foxp3 in tumor infiltrating Treg cells, which critically specifies the Treg lineage and maintains its functional program." (PMID 32477338, 2020). "CCL5 was directly transactivated by cancer-Foxp3 and promoted the recruitment of Tregs from peripheral blood to the tumour site." (PMID 32680511, 2020). "Using immunohistochemical staining, expression of vimentin, CD8, FOXP3, programmed cell death protein 1 (PD-1), and programmed cell death ligand 1 (PD-L1) were evaluated in resected tumor tissue." (PMID 32850341, 2020). "There was no significant change in CD8+Ki67+, CD8+Granzyme B+, CD4+, and Foxp3+ (Treg) T cells compartment in the spleen and tumor." (PMID 32780726, 2020). "Recent evidences suggest that HCC tumor microenvironment is enriched with Foxp3+CD4+ and PD-1+CD8+ T cells which together provide an extensive immunosuppressive microenvironment." (PMID 33014820, 2020). "This is in accordance with the idea that a correlation between Foxp3 expression and tumor progression during CRC exists." (PMID 32674255, 2020). "FOXP3 plays a very important role in Treg cells, preventing cytotoxic T cells from attacking tumor cells." (PMID 32964032, 2020). "FOXP3 expression in tumor cells was extremely statistically significant when correlated with the Breslow depth (t test, two-tailed P value < 0.0001)." (PMID 33274240, 2020). "These HDC+ BMMCs support tumor infiltration of CD4+ FOXP3+ Tregs and strongly support colonic tumorigenesis of CRC." (PMID 33419310, 2020).
tumor (continued). "Treg cells are a subset of CD4+ cells that specifically express the forkhead box protein P3 (FoxP3) and play a key role in modulating the antitumor T cell responses in the tumor microenvironment." (PMID 32359357, 2020). "Compared with PN, MES exhibited enhanced immunosuppression by being enriched for more tumor-associated macrophages (TAMs), CD3+, and FOXP3+ T cells." (PMID 33028341, 2020). "With respect to prognosis, they observed that a high infiltration of FOXP3+ TILs within tumor bed was a predictor of poorer disease-free and overall survival." (PMID 32401825, 2020). "Assessing the bacterial load in tumor samples with different stromal phenotypes showed that an increased bacterial content is typical for tumors with high iNOS (p = 0.0170) and FOXP3 (p = 0.0292) expression." (PMID 32933105, 2020). "The proportion of CD45+CD3+CD8+ expressing T-cells and CD45+CD4+CD25+FoxP3+ expressing regulatory T-cell (Treg) cells remained unchanged in 3 × 5 Gy RT-treated tumours compared to untreated control tumours." (PMID 32641865, 2020). "A new regulatory subset of γδ T cells that express Foxp3, termed γδ regulatory T cells (γδ Tregs), has been confirmed to be at a low frequency in tumor-infiltrating leukocytes (TILs) and human PB." (PMID 32802845, 2020). "The presence of intratumoral FOXP3-positive lymph cells was correlated, in our study, with FOXP3 expression in tumor cells." (PMID 33274240, 2020). "Consistent with previously data, administration of CTLA-4 mAbs after tumor challenge resulted in a reduced frequency of Foxp3+ cells in the B16-IL36 tumor." (PMID 32351508, 2020). "Patients with OSCC and high density of FoxP3+ T-cells in the IF of tumor parenchyma showed significantly increased OS (91.7% vs. 73.8%, p = 0.006), DSS (95.8% vs. 84.6%, p = 0.02), RFS (73.6% vs. 50.8%, p = 0.008), and MFS (87.7% vs. 70.6%, p = 0.02)." (PMID 32785290, 2020). "In this line, accumulating studies have demonstrated that a large number of Treg cells and a decreased ratio of tumor-infiltrating CD8+ T cells versus FOXP3+ Treg cells were shown to correlate with poor prognosis in different types of cancer including NSCLC." (PMID 32580514, 2020). "Experiments detected a significant reduction of tumor-infiltrating FoxP3+ Treg and granulocytic MDSC (G-MDSCs) (vs. monocytic MDSC, M-MDSC) in mice receiving entinostat treatment." (PMID 32158754, 2020). "Treg, defined as CD4+ CD25+ Foxp3+ T cell, is capable of immunosuppression which helps tumor cells escape from the immune system, accounting for poor prognosis in a variety of solid malignancies." (PMID 32685487, 2020). "The numbers of tumor-infiltrating FoxP3+ T-cells were as follows: TCe parenchyma (range 0–29; median 2), TCe stroma (range 0–96; median 16), IF parenchyma (range 0–23; median 2), and IF stroma (range 0–122; median 28)." (PMID 32785290, 2020). "In contrast, a clinical study with NSCLC patients revealed that the accumulation of CD4+ FOXP3- PD-1 high T cells within the tumor and peripheral blood correlated with higher tumor burden." (PMID 33329566, 2020). "The results showed that the expression level of Foxp3 mRNA in lymphocytes of mice in the tumor-bearing model group increased significantly, while the expression level of Foxp3 mRNA in the solanine treatment group decreased significantly, with a time effect." (PMID 33204731, 2020). "For example, the prognostic role of FoxP3(+) Tregs is influenced by tumor site, stage, and molecular subtype." (PMID 33396205, 2020). "Especially, FOXP3+ regulatory T cells, which are also known as CD4+CD25+ Tregs, have suppressive effects on the anti-tumor immunity, and have been associated with poor clinical outcome." (PMID 32401825, 2020). "The expressions of Foxp3 and TGFβ in the transplanted tumor tissues of mice in the solanine group were significantly lower than those in the control group." (PMID 33204731, 2020).
tumor (continued). "On the contrary, FOXP3+ T-cell infiltration was found to predict a worse prognosis via the mediation of tumor immune escape." (PMID 32131780, 2020). "IR increases the infiltration of various subtypes of T cells, including CD4+, CD8+ and Foxp3+ T cells, into the tumour area." (PMID 32284765, 2020). "There were evaluated correlations of the most important prognostic factors (Breslow depth and mitotic index) with FOXP3 expression in tumor cells and with the presence of regulatory T cells and dendritic cells in the tumoral stroma." (PMID 33274240, 2020). "CD4+CD25+FOXP3+ effector regulatory T cells (Tregs) infiltrate into the tumor stroma as well as tumor-draining lymph nodes and potently suppress anti-tumor immunity." (PMID 33324425, 2020). "Patients with a high number of FOXP3+ T cells in their tumor had a median survival time of 58 months, while those with a low FOXP3+ T cells count had a median survival time of 32 months." (PMID 32377339, 2020). "We characterized the antitumor response by mapping infiltration of CD4+ and FOXp3+ cells in the tumor microenvironment." (PMID 32469935, 2020). "The immunohistochemistry results indicated that CD11b, Gr-1 and Foxp3 were highly expressed in the tumours of the IL-35 group and less expressed in those of the IL-35 NA group (p < 0.01)." (PMID 33041668, 2020). "With regard to Tregs, migration of CD4+Foxp3+ T cells to the tumor microenvironment is an independent factor for poor prognosis." (PMID 33121123, 2020). "We used the APCMin/+\DEREG mouse model, which harbor a diphtheria toxin receptor under the control of the FOXP3 promoter, to deplete Treg in tumor bearing mice." (PMID 32185408, 2020). "FOXP3 is a valid target for identifying Treg in the tumor microenvironment and contributes significantly to Treg cells differentiation and mediated tumor immune escape." (PMID 33628726, 2020). "Fc-region–modified anti-CTLA-4 mAb with high antibody-dependent cell-mediated cytotoxicity (ADCC) and cellular phagocytosis (ADCP) activity selectively depleted CTLA-4+Foxp3+ Tregs and consequently expanded tumour antigen-specific CD8+ T cells." (PMID 32680511, 2020). "Several studies demonstrate that FOXP3+ Tregs infiltrating tumor suppress CD8+ T cells to maintain immunological tolerance and associate with advanced tumor growth and poor prognosis in several types of malignant tumors." (PMID 32884895, 2020). "A significantly greater number of CD8+ CTLs, and significantly fewer FoxP3+ Tregs, were found in tumors of the groups receiving the cytokine gene transduction and DC treatment, which yielded significantly better results in tumor therapy." (PMID 32123853, 2020). "V-domain Ig suppressor of T-cell activation (VISTA) is a receptor present in the whole population of tumor-infiltrating lymphocytes; however, its activation suppresses specifically only the T-cell response, while stimulating the expression of FOXP3." (PMID 33114418, 2020). "In the present study we analyzed the CD8+ and FOXP3+ T cells localized along the stromal–tumor interface at tumor edge in dermis (peritumoral) and those completely surrounding the neoplastic cells (intratumoral)." (PMID 33117345, 2020). "Regulatory T cells (Tregs), which normally function as an immunosuppressing agent through expression of FOXP3, acquire enhanced effectiveness in the tumor microenvironment (TME)." (PMID 33262947, 2020). "qPCR analysis revealed that the mean relative expressions of VEGF-A, VEGFRs, and Foxp3 genes in the post-vaccination tumors were lower than that of the pre-vaccination tumor." (PMID 32164575, 2020). "Some immune cell types have immunosuppressive properties and can facilitate tumor growth—for example, FOXP3+ regulatory T cells and interleukin-10-secreting B cells." (PMID 33276550, 2020). "As it is not possible to distinguish between the CD4+ T cells with low and high expression of FOXP3 in tumor tissues by conventional immunohistochemistry, this remains a limitation of our study." (PMID 32377339, 2020).
tumor (continued). "STAT3 has also been confirmed as a critical molecular driver for FoxP3 expression and Treg immunosuppressive phenotype in the tumor setting." (PMID 33335857, 2020). "Quantification of immunolabelled cells in situ confirmed increased CD8+ CTLs and CD4+ Th cells, with FoxP3+ Treg cell numbers remaining unchanged in the Cx3cr1‐Rheb1Δ/Δ tumours." (PMID 32567735, 2020). "In vivo, COX-2 inhibition reduces Treg cell frequency and activity, attenuates Foxp3 expression in tumor-infiltrating lymphocytes (TILs), and decreases tumor weight." (PMID 33271839, 2020). "82% of CHL cases, regardless of the subtype, expressed VDR and in majority of the cases, VDR expression was directly proportional to the quantity of FOXP3 expressing lymphocytes in the tumor microenvironment." (PMID 32513132, 2020). "In multivariate analysis, we found that a higher number of CD4+FOXP3+ T cells in the tumor core was an independent predictor of prolonged survival (HR = 0.238, P < 0.001)." (PMID 32377339, 2020). "The detection methods selected, and the reagents used are critical for the study of tumor FOXP3 and isoforms in tissue samples." (PMID 33116119, 2020). "FoxP3+ T-cells can inhibit inflammatory processes in the tumor microenvironment, favoring tumor progression." (PMID 32785290, 2020). "Unexpectedly, we found that CD25+FoxP3+ Tregs were significantly increased within the tumor microenvironment when agonistic CD40 mAb therapy was combined with epacadostat." (PMID 32231867, 2020). "CTLA-4 antibody induces anti-tumor immunity by blocking Foxp3+Treg cells in the tumor microenvironment and AKT phosphorylation pathway, effectively amplifying T cells and enhancing the anti-tumor effect." (PMID 33033520, 2020). "In colorectal and esophageal cancers, the presence of hybrid Th17/Treg cells expressing both IL-17, RORγt and Foxp3 were identified by flow cytometry in the tumor and in the peripheral blood of patients." (PMID 32121394, 2020). "In frailer patients (G8 ≤ 14), the proportion of FOXP3+ cells was higher in the invasive front (P = 0.015) and whole tumor (P = 0.007), as compared to fit patients (G8 > 14), and the density of FOXP3+ cells was also increased in the tumor centre (P = 0.037)." (PMID 33024560, 2020). "FOXP3+ Treg is thought to promote tumor growth and metastasis by inhibiting anti-tumor immunity, and Treg accumulation in cancer is usually related to poor prognosis." (PMID 33194642, 2020). "Fluorescence-activated cell sorting (FACS) analysis of tumor cell populations revealed that among Foxp3+ cells, 40% were Siah2−/− and 60% were Siah2 WT." (PMID 31911617, 2020). "This is especially valid in view of the observed diversity in Treg populations in cancer and the divergent results from studies which have utilized FOXP3+ to examine tumor-infiltrating Treg." (PMID 33013886, 2020). "Whereas in interstitial lymphocytes, most of FoxP3 staining was detected in the cytoplasm with some cells exhibiting nuclear expression, only discrete FoxP3+ dots were found in the nucleus of tumor cells." (PMID 32123292, 2020). "Meanwhile, we found that the absence of follicular regulatory T (Tfr) cells, which is a result of Bcl6 deletion in Foxp3+ cells, was dispensable for tumor control." (PMID 32477338, 2020). "As expected, both CCL22 and Foxp3 (marker of Tregs) mRNA levels were increased in tumor samples when compared with in adjacent normal tissues." (PMID 31769216, 2020). "Cox regression models for survival, immunohistochemical, clinical, and pathological findings (tumor-infiltrating FoxP3+ T cells)." (PMID 32785290, 2020). "Chronic exposure to low IFN-γ levels in H22 hepatoma, MA782/5S mammary adenocarcinoma and B16 melanoma led to tumor development and induction of PD-L1, PD-L2, CTLA-4 and Foxp3 molecules which at least partially mediated tumor immune evasion." (PMID 33005420, 2020).